MET (MET proto-oncogene, receptor tyrosine kinase)
Diseases named in the same sentence as MET in open-access papers (continued):
Sharing a sentence is not in itself a finding about the gene and the disease.
melanoma (continued). "We have previously shown that combination of foretinib, an inhibitor of MET (hepatocyte growth factor receptor), with gefitinib or lapatinib, inhibitors of EGFR (epidermal growth factor receptor), has a synergistic cytotoxic effect on melanoma cells." (PMID 31649529, 2019). "Thus, melanoma cell proliferation, survival, and acquisition of the metastatic phenotype can be supported by autocrine HGF/c-MET signaling." (PMID 30513872, 2018). "Overexpression of HGF and c-MET in melanoma cells enhances cell protection from cell death, which was shown to be mediated by the activation of the MAPK/ERK and PI3K/AKT pathways, frequently modified in melanomas." (PMID 30513872, 2018). "Next, melanoma cells were exposed to either PLX-4720 or PD-184352 (MEK1/2 inhibitor) in the presence of increasing concentrations (6.25–50 ng/mL) of recombinant HGF, HGF-neutralizing antibodies, or crizotinib, a MET inhibitor." (PMID 30513872, 2018). "Hepatocyte growth factor (HGF) secreted by fibroblasts leads to the resistance of BRAF-mutant melanoma to RAF inhibition via activation of the MAPK pathway, the PI3 K/AKT pathway, and the HGF receptor MET, while similar phenomena also appear in colorectal cancer." (PMID 30038550, 2018). "MET activation, which may be driven by stromal HGF expression, has been shown to mediate melanoma growth, dissemination, and resistance to BRAF inhibition in multiple preclinical models." (PMID 28103611, 2017). "The oncogenic signaling loop of HGF/SF and MET is also not represented in other GEMM systems as they often utilize the BRAFV600E mutation, which is only present in 35–50% of human melanomas, to aid in the induction of melanomas." (PMID 28788083, 2017). "In addition, we showed that MAPK pathway inhibition induced rapid increases in MET and GAB1 levels, providing novel mechanistic insight into how BRAFV600E mutant melanoma is primed for HGF-mediated rescue." (PMID 28147313, 2017). "The unique role of HGF/MET signaling in conferring resistance to MAPK pathway inhibitors in BRAF and NRAS mutant melanoma suggests that combination therapy with small-molecule MET inhibitors may provide additional benefit beyond BRAF and MEK inhibitors alone." (PMID 28147313, 2017). "There is a strong rationale for targeting MET, AXL, and VEGFRs in melanoma." (PMID 28103611, 2017). "Thus, our results indicate a regulatory role of GH on expression of HGF, MET and ERBB3 in human melanoma cells." (PMID 28223541, 2017). "Taken together these data suggest that the increases in total MET and GAB1 may prime BRAF mutant melanoma cells for HGF-mediated rescue." (PMID 28147313, 2017). "In addition to TGFβ and WNT5A signaling, EGF, FGF, MET, and IGF signaling have established roles in conferring migratory and invasive functions in melanoma." (PMID 25763355, 2015). "Caenepeel and colleagues reported that HGF rescued melanoma cell lines,notably SK-MEL-5, from BRAF or MEK inhibition using vemurafenib (an analogue of PLX4720)or PD0325901, respectively, and the rescue was attenuated by MET inhibition." (PMID 25490933, 2014). "Although miR-31 has been shown to act as either an oncomiR or tumor suppressor in various tumor types, in this study we clearly establish miR-31 as a tumor suppressor, demonstrate that it targets multiple oncogenes such as SRC, MET, NIK and RAB27a and regulates the expression of EZH2 in melanoma." (PMID 22948084, 2012). "Transient overexpression of miR-31 in various melanoma cell lines inhibited cell migration and invasion, supporting a role for miR-31 as a tumor-suppressive miR that targets multiple oncogenes such as SRC, MET, NIK and RAB27a." (PMID 22948084, 2012). "In neural crest, melanocyte, and melanoma cells, PAX3 was found to regulate MITF, NGN2, RET, SOSTDC1, MSX2, DCT, and TYRP1 genes, as well as genes expressed ubiquitously or widely (and including melanocytes), such as BCL-XL, CXCR4, FGFR4, HES1, MET, NF1, TGFb2, and WNT1." (PMID 40428399, 2025).
melanoma (continued). "Targeting the c-MET with inhibitors such as PHA-665752 and ARQ197 (tivantinib) demonstrated significant responses in brain metastasis-derived cell lines in vivo, suggesting the potential of MET-targeted therapy in managing melanoma brain metastases and improving patient outcomes." (PMID 39582535, 2024). "MET inhibitors are often not effective as single‐therapy agents in melanoma in clinical studies, which may be related to the interaction of the MET based pathways with other oncogenic pathways." (PMID 37679999, 2023). "Therefore, tumour cells also use its activity to promote tumour progression, but, unlike melanocytes, melanoma cells are able not only to express c-MET, but also to release HGF in an autocrine manner for self-stimulation." (PMID 37022605, 2023). "MACC1 expression does not appear to correlate with MET expression in nevi and primary melanomas." (PMID 37496665, 2023). "Other studies showed that six out of 16 melanoma tumors acquired EGFR expression after the development of resistance to BRAF or MEK inhibitors, and acquired resistance was found with the overexpression of signaling receptors like EGFR, PDGFRβ, or MET that reactivation the MAPK pathway." (PMID 34360915, 2021). "Hepatocyte growth factor (HGF), via stimulation of its cognate receptor c-MET, and activation of the downstream effector components (MAPK, STAT, PI3K-AKT cascades and NF-κB), increases the survival, motility and proliferation of several cell types of cancer cells, including melanoma cells." (PMID 33276788, 2020). "Interestingly, in case of MET expression, only the tissue origin of the cells does not explain the differences among melanoma and colon cell lines." (PMID 33081092, 2020). "Thus, we can propose that inhibition or activation of the protein kinases such as AKT, HIPK2, AMPK, MET, JNK, HIF-1α, and CD44 by treatment with CDPs in the mouse melanoma model could involve the blocking of the substrate binding site as a molecular mechanism." (PMID 32793477, 2020). "The hypothesis is supported by experiments that indicate c-MET positive CD8 positive cells have increased ability to reduce melanoma pulmonary metastasis compared to c-MET negative CD8 positive cells, which can be abrogated by the addition of HGF." (PMID 32117721, 2020). "However, MET expression is not controlled exclusively by MITF, as no tight correlations were observed between MITF level and MET expression in other melanoma cell lines." (PMID 30513872, 2018). "In summary, these findings add significant and novel mechanistic insight into the potential role of HGF/MET signaling in mediating resistance to BRAF and MEK inhibitors and support the clinical evaluation of MET kinase inhibitors and HGF-neutralizing antibodies in melanoma." (PMID 28147313, 2017). "In addition, in a subfraction of primary and metastatic melanomas, co-expression of MYSM1 with c-MET could be verified." (PMID 28978033, 2017). "In addition, α-MSH also regulates the MET proto-oncogene expression in both melanoma cells and in normal human melanocytes." (PMID 24416311, 2014). "Additionally, PHA665752, a drug that blocks MET phosphorylation, has shown to be effective in targeting NRAS-mutant cells during in vitro studies, indicating the broader effectiveness of Met inhibitors in treating various melanoma subtypes, not only the common BRAFV600E mutant." (PMID 38732242, 2024). "TCGA analysis detected fusions in BRAF and RAF1 kinases in melanomas, but did not report fusions in ALK, ROS1, MET, RET, or NTRK, which are clinically targetable." (PMID 34831002, 2021). "In two different melanoma cell lines (SK-MEL-28 and HT144), we observed that transient knockdown of BRN2 reduced c-MET protein levels, whereas knockdown of MITF had no visible effect on c-MET level." (PMID 32632141, 2020).
melanoma (continued). "Moreover, proteins related to melanoma biology (e.g., MET, CSPG4/MCSP) were specifically upregulated in melanoma compared to healthy EVs, but showed no differential abundance in depleted plasma, showing the sensitivity and specificity of the EV preparation." (PMID 38353833, 2024). "In our series, patients with BRAF and MET genetic alterations did not receive any targeted treatment because no such treatment were available at the time of the study, despite BRAF was a well-established therapeutic target in other malignancies like melanoma." (PMID 35012520, 2022). "Exposure to 0.25 μm crizotinib, an inhibitor of c-MET, after induction of BRN2 expression led to a significant decrease in cellular viability in non-adherent conditions in all three melanoma cell lines examined (MM370, p = 0.0029; MM455, p = 0.02; MM603, p = 0.0039)." (PMID 32632141, 2020). "In BRAFV600E mutant melanoma, where robust MAPK pathway signaling is present, we hypothesized that MET and GAB1 levels were repressed by an ERK-dependent negative feedback mechanism." (PMID 28147313, 2017).
glioblastoma (254 papers, 2008 to 2026). The most malignant astrocytic tumor (WHO grade IV). "Activating mutations in the MET gene are pivotal in the transition of low‐grade gliomas to secondary glioblastomas and contribute to the pathogenesis of glioblastoma." (PMID 41521799, 2026). "For example, the 404-amino-acid MET variant (MET404) encoded by circMET promotes glioblastoma invasiveness through interaction with the β subunit of MET kinase to form a constitutively activated MET receptor complex." (PMID 40513780, 2025). "This fusion is caused by a translocation event involving intron 3 or 8 of PTPRZ and intron 1 of MET, is found in about 14% of secondary glioblastomas (i.e., astrocytoma, IDH mutant, WHO grade 4), and causes the activation of MET signaling." (PMID 35457233, 2022). "Detailed analysis of bulk and single-cell glioblastoma transcriptomes associates the cellular subpopulation over-expressing c-MET with inflamed, hypoxic, metastatic, and stem-like phenotypes." (PMID 33859738, 2021). "The findings of an inhibitory effect on HGF/c-MET by TGF-β in vitro prompted us to validate an association between the two pathways in vivo using human glioblastoma specimens." (PMID 29238047, 2017). "However, in cancer, Met activity promotes the proliferation, survival and migration of tumors, and in glioblastoma, MET overexpression is linked to resistance to chemotherapy." (PMID 39518074, 2024). "Moreover, the upregulation of c-MET has been found after EGFR monotherapy in glioblastoma stem cells (GSCs) in vitro, causing long-term self-renewal ability in these cells." (PMID 39272879, 2024). "Dysregulation of the c-MET pathway has been implicated in the pathogenesis of glioblastoma." (PMID 38264122, 2023). "We have thus asked whether c-MET mutated iPSC could allow modeling glioblastoma, a tumor in which an overexpression of c-MET has been described in 10% of cases." (PMID 34722569, 2021). "Moreover, bevacizumab-treated glioblastoma patients have an increased relapse in comparison to bevacizumab-untreated patients, linked to an upregulation of c-MET and phospho-c-MET." (PMID 34298648, 2021). "However, it is interesting that glioblastomas expressing PTPRZ1-MET often also express METΔEx14 splice variant, suggesting that MET activation in these tumors may be complex." (PMID 40361420, 2025). "Moreover, TERTp mutation tended to co‐occur with EGFR, KRAS, and MET in glioblastoma." (PMID 39804195, 2025). "Our results recommend OV-encoded dual-targeting antibodies and more specifically the Db-TriTE-encoding oAd Ad5/3-DMFE for dual-targeting of EGFR and c-MET frequently co-expressed in NSCLC, glioblastoma, and colorectal cancer." (PMID 41552759, 2026). "Research has revealed the presence of MET fusion transcripts in secondary glioblastomas, highlighting their potential as a drug target in both adult and pediatric glioblastoma cases." (PMID 41521799, 2026). "The role of MET exon 14 in secondary glioblastomas has been clarified, showing its contribution to glioma progression." (PMID 41521799, 2026). "Since this discovery, several additional MET gene fusions have been observed, particularly in pediatric glioblastomas." (PMID 40361420, 2025). "Knockdown of the circMET gene was also shown to repress the expression of MET 404 in mice, while high expression of MET 404 further exacerbates glioblastoma tumorigenicity in vivo and in vitro." (PMID 41208886, 2025). "The drug effects were also tested on c-MET-positive orthotopic E98 glioblastoma xenografts and it is a promising therapy for c-MET-positive glioma." (PMID 40076810, 2025). "For example, secondary adult glioblastoma, in which MET-fusions have been identified in up to 15%, potentially represent another promising and eligible entity for concomitant capmatinib-radiation treatment in addition to pHGG." (PMID 38849845, 2024). "Among 55 glioblastoma cases, gene fusions were detected in 11 cases (20%), including novel MET fusions." (PMID 38363490, 2024).
glioblastoma (continued). "Gains in chromosome 7 are also common in glioblastomas and are associated with mutations or amplification of oncogenes such as EGFR and MET." (PMID 39518074, 2024). "PTPRZ1–MET fusions connecting the first one, two, three or eight exons of the receptor tyrosine phosphatase PTPRZ1 with exon 2 of MET just before the open reading frame (ORF) start codon have been previously reported in glioblastoma." (PMID 38254850, 2024). "In parallel, single-cell transcriptome analysis has brought to the forefront the critical functionality of c-MET signaling within glioblastoma cells navigating the hypoxic TME." (PMID 39664377, 2024). "This phenomenon was further validated in in-vitro experiments where we co-cultured the c-MET-knockdown glioblastoma cell line with the Jurkat T cell line." (PMID 38352883, 2024). "MET inhibitors have already shown promise in the treatment of PTPRZ1-MET fusion-driven pediatric glioblastoma, with improved clinical and radiological responses over a period of 2 months." (PMID 39409964, 2024). "Aberrant splicing to produce EGFR exons 2-7 skipping mRNA, and MET exon 14 skipping mRNA were identified in glioblastoma and pancreas carcinoma BM, respectively." (PMID 39087020, 2024). "Quercetin reduces the migration, invasion, and tumorsphere formation of prostate CSCs, whereas apigenin inhibits the growth and metastatic potential of glioblastoma stem cells by blocking c-MET signaling." (PMID 38201226, 2023). "Crizotinib is another selective c-MET inhibitor that had encouraging results in phase I clinical trials in newly diagnosed glioblastoma patients." (PMID 37857607, 2023). "Yet, these preclinical data suggest that MET pathway inhibition in human glioblastoma would be best explored in combination with radiotherapy." (PMID 36915128, 2023). "There is also increasing interest in the role of the HGF/MET pathway in the response of glioblastoma to radiotherapy." (PMID 36915128, 2023). "In glioblastoma, the MET-Capza2 reassembly is mediated by eccDNA, and this fusion transcript prompts the overexpression of the MET oncogene." (PMID 39534571, 2023). "The hepatocyte growth factor (HGF)/MET signaling pathway has been proposed to be involved in the resistance to radiotherapy of glioblastoma via proinvasive and DNA damage response pathways." (PMID 36915128, 2023). "Activated by its single ligand, hepatocyte growth factor (HGF), the receptor tyrosine kinase MET is pivotal in promoting glioblastoma (GBM) stem cell self-renewal, invasiveness and tumorigenicity." (PMID 37491377, 2023). "Foretinib has been found to reduce the phosphorylation of c-MET in glioblastoma multiforme cells and inhibit glioblastoma cell proliferation through G2/M cell cycle arrest and mitochondria-mediated apoptosis." (PMID 37263638, 2023). "The HGF/MET pathway is potentially involved in all these processes, and there is strong support from preclinical studies for targeting this pathway in glioblastoma." (PMID 36915128, 2023). "The flavonoid apigenin inhibits the self-renewal and invasion abilities of glioblastoma stem cells through the suppression of c-MET signaling." (PMID 38201226, 2023). "As a consequence, MET inhibitors demonstrate clinical efficacy when initially administered to glioblastoma patients; however, unfortunately, the acquired resistance to these agents frequently ensues and hampers their prolonged use." (PMID 35743016, 2022). "Conversely, mesenchymal subtype glioblastomas were characterized by high expression of chitinase 3 like 1 (CHI3L1) and tyrosine-protein kinase Met (MET), a high frequency of neurofibromin 1 (NF1) mutation/deletion, and low NF1 gene expression." (PMID 36591531, 2022). "Bypass mechanisms to crizotinib and another MET inhibitor, onartuzumab, were recently discovered in glioblastoma." (PMID 35743016, 2022).